EGF (epidermal growth factor)
Diseases named in the same sentence as EGF in open-access papers (continued):
Sharing a sentence is not in itself a finding about the gene and the disease.
lung carcinoma (continued). "A bioinformatics analysis indicated that in female patients with non‐small cell lung cancer (NSCLC), EGF may be an important gene in the mechanisms of NSCLC onset and prognosis, representing a potential therapeutic target." (PMID 40696566, 2025). "The EGF and its receptor EGFR play a significant role in lung cancer." (PMID 38905286, 2024). "In the A549 lung cancer cell line (in which EGF receptors are overexpressed), the phosphorylation levels of ERK1/2, STAT3, and AKT1 were not altered by GTN057 when these cell lines were activated by epidermal growth factor (EGF) stimulation." (PMID 36825580, 2023). "EGF activates EGFR signaling and promotes lung cancer cell proliferation, invasion, and metastasis." (PMID 37990309, 2023). "Other clinical trials have focused on the development of new EGF/EGFR targeted therapies, such as monoclonal antibodies and TKI, which may provide patients with lung cancer with better therapeutic alternatives." (PMID 37760616, 2023). "The EGF and VEGF families are the primary targets in this approach, and several studies are being conducted to propose anti-angiogenic drugs that are increasingly suitable for the treatment of lung cancer, either as monotherapy or as combined therapy." (PMID 37760616, 2023). "In a tumoral context, delphinidin has been reported to decrease levels of EGF-induced VEGF-A expression in prostate and lung cancer cells, by a mechanism involving the inhibition of HRE-promoter activity in response to EGF induction, and the blockage of ERK and PI3K/Akt pathways." (PMID 35213989, 2022). "A high EGF amount plus EGFR overexpression in lung cancer cells, create conditions for the growth of some EGF-dependent tumors, even in the absence of specific EGFR driver mutations." (PMID 34211836, 2021). "Our data demonstrated that MRTF-A depletion impedes EGF- and serum-induced cancer cell migration, which is consistent with previous results implicating MRTF-A as an oncogene in leukemia, pancreatic cancer, and lung cancer." (PMID 33842533, 2021). "Another approach proposed lipid polymeric nanoparticles (hydrophobic polymeric core, phospholipid layer and an outer layer of epidermal growth factor (EGF), PEG and distearoylphosphoethanolamine) targeting the EGF receptor (EGFR), which is overexpressed in lung carcinoma." (PMID 31973051, 2020). "EGF treatment induced MTHFD2 expression in H322, but little, if any, in A549 lung cancer cells." (PMID 30532069, 2019). "Collectively, these findings indicate DUOX1 silencing in lung cancer cells impacts on EGFR internalization and nuclear translocation in response to EGF, with corresponding consequences for EGFR-mediated cell proliferation and migration, as well as sensitivity to (antibody-based) EGFR targeting." (PMID 30890751, 2019). "A549 lung cancer cells were pretreated with propolin C, LY294002, and PD98059 alone, respectively, or were cotreated with LY294002 and PD98059 with propolin C for 30 min and then stimulated with EGF for 24 h." (PMID 29681982, 2018). "Additionally, EGF-induced PI3K/Akt and ERK activation was inhibited by propolin C in EGFR wild-type A549 lung cancer cells." (PMID 29681982, 2018). "Moreover, reversing EGF-induced migration and invasion and EMT changes were observed in propolin C-treated EGFR wild-type A549 lung cancer cells." (PMID 29681982, 2018). "In addition, propolin C also inhibited EGF-induced migration and invasion as well as mesenchymal-like markers expressions in EGFR wild-type lung cancer cells." (PMID 29681982, 2018). "To confirm the role of NEDD4 in lysosomal secretion, we detected the secreted lysosomal protease cathepsin B in culture medium using an ELISA assay in both the vector control and the shNEDD4 lung cancer A549 cells with or without EGF stimulation." (PMID 29455656, 2018). "Therefore, targeting EGF/EGFR signaling pathway to attenuate cancer cell tumorigenesis is the strategy for preventing and/or improving lung cancer patient prognosis." (PMID 29681982, 2018).
lung carcinoma (continued). "The lysosomal protease cathepsin B is important for both the EGF and the non-EGF dependent lung cancer cell migration." (PMID 29455656, 2018). "Treatment of the cells with 10 μM CA-074Me significantly inhibited both the non-EGF-dependent (basal) and the EGF-stimulated lung cancer cell migration." (PMID 29455656, 2018). "As for the experiments for the EGFR binding assay carried out with human lung carcinoma A549 cells, images were taken 1.5 hours after the cells being in contact with EGF and for the negative control." (PMID 27788212, 2016). "Importantly, MMP9 inhibition decreased the TNF-α- and EGF-stimulated invasiveness of A549 cells, highlighting the importance of the S100A4/MMP9 axis in S100A4-driven invasion in lung cancer cells." (PMID 27127879, 2016). "It is important to mention that EGF, an important growth factor playing a major role in lung cancers, is not measurably expressed in non-infected cells, whilst in HBoV infections the expression leads to strong signals and high RDMs." (PMID 26807786, 2016). "It has been reported that lung cancer- derived EGFR active- site mutants are constitutively active and thus oncogenic, even without EGF, and that this activation is probably caused by interaction with Src." (PMID 25803810, 2015). "For instance, Twist1 expression is associated with EGFR mutation in lung adenocarcinoma from non-smokers, and a cooperative effect between EGF pathway activation and Twist1 reactivation promotes EMT in EGFR mutated lung cancer." (PMID 26360779, 2015). "Tyr residues in EGFR of the lung cancer cells overexpressing DDX3X were not phosphorylated even in the presence of EGF." (PMID 25343452, 2014). "Interestingly, we found that EGF-induced EGFR endocytosis is existed differently between gefitinib-sensitive and -insensitive lung cancer cell lines." (PMID 24658031, 2014). "For example, miR-125 expression is reduced in human lung cancer cell culture due to epidermal growth factor (EGF) stimulation, though it is not yet clear which transcription factors are involved in this response." (PMID 24427166, 2013). "We further examined a variety of squamous carcinoma cells, including A431 esophageal carcinoma, EBC1 lung carcinoma, LK2 lung carcinoma, OSC19 oral carcinoma and HSC3 oral carcinoma cells, and found that all of them migrated similarly in response to EGF in this assay." (PMID 23704935, 2013). "Mutations in EGFR and KRAS are mutually exclusive in both human and murine NSCLC, and EGF stimulation would not be expected drive Kras mutant models of lung cancer." (PMID 21699731, 2011). "We performed RNAseq analysis on A549 lung cancer cells and 122L and 153L (HMEC cultures derived from post-menopausal women), and 240L (HMEC cells derived from an 18-year-old woman) that had been treated with EGF (A549 only), TGF-β1 (HMEC only), or IL-6 (both A549 and HMEC) for six hours." (PMID 41497628, 2025). "Moreover, release of adrenaline and noradrenaline, the physiological ligands for β-AR, upon binding of nicotine to α7nAChRs, activates the β-AR which, in turn, stimulates release of EGF and IGF, thereby promoting growth and proliferation contributing to lung cancer progression." (PMID 36361620, 2022). "We can find no prior literature on this topic but our results suggest EGF may contribute to the fitness of these lung cancer cells perhaps though complementary signaling circuits." (PMID 36612014, 2022). "In a mouse model of lung cancer, the adaptor protein, TBK-binding protein 1 (TBKBP1), has been shown to mediate PKCθ direct phosphorylation of TANK-binding kinase 1 (TBK1) in response to epidermal growth factor (EGF) stimulation, leading to the activation of the oncogenic activity of TBK1." (PMID 33562506, 2021). "Interestingly, treating A549 lung carcinoma cells with OA or EGF, which enhanced or suppressed tumour cell exosome release, respectively, we found that the level of PKM2 in A549 cells was dose-dependently decreased by OA or increased by EGF." (PMID 28067230, 2017).
lung carcinoma (continued). "This as opposed to the EGF-insensitive cell line, H460, which is a large cell lung cancer." (PMID 29029422, 2017). "In addition, EGF stimulation resulted in simultaneous TOPK and c-Jun phosphorylation, both in HEK293 cells and H358 cells that expressed ectopic TOPK and in EGFR-TKI-resistant A549 and H1975 lung cancer cells that expressed high endogenous TOPK." (PMID 26745678, 2016). "The fact that both nicotine and EGF could induce the expression of ID1 in a Src-dependent manner raises the possibility that ID1 might be contributing to the genesis of lung cancers in both smokers and nonsmokers." (PMID 25028095, 2014). "Given the importance of EGFR signaling as a therapeutic target in lung cancer, further examination of the effect of EGF, heregulin, and amphiregulin on GPER expression and function in lung cancer may provide new insights into resistance to EGFR inhibitors and or how estrogens stimulate lung cancer." (PMID 23273253, 2012). "Serum concentrations of Epidermal Growth Factor, sCD26, Calprotectin, Matrix Metalloproteinases −1, −7, −9, CEA and CYFRA 21.1 were determined in 140 patients with respiratory symptoms (lung cancer and controls with/without benign pathology)." (PMID 28117344, 2017). "Although the in vivo role of IL10 in lung cancer has not been previously elucidated, in this study, we showed that IL10 was highly increased in lung cancer, and EGF promoted proliferation by increasing IL10 secretion." (PMID 26956044, 2016). "However, we found that in DMS114 cells and other EGFR-positive lung cancer cells such as HCC15, EGF administration did not affect the cytotoxicity of taltobulin." (PMID 37509496, 2023). "To examine whether the endogenous EGFR-AURKA interactions exist in lung cancer cells and whether it is EGF dependent, we applied in situ PLA to determine the EGFR-AURKA interaction in A549 and H1975 with or without EGF stimulation." (PMID 23520446, 2013). "However, the functions of EGF and GM6001 on invadopodia formation in lung cancer invasion have not been studied yet." (PMID 23441195, 2013). "Furthermore, to validate that G9a regulates the stemness property in lung cancer and understand whether it downregulates EGFR signaling in lung cancer cells, UNC0642 was co-treated with or without EGF in HCC827 cells." (PMID 28787001, 2017).
glioma (212 papers, 2000 to 2025). A benign or malignant brain and spinal cord tumor that arises from glial cells (astrocytes, oligodendrocytes, ependymal cells). "Mutations in the epidermal growth factor (EGF) have been implicated in gliomas’ resistance to conventional chemotherapy." (PMID 39184045, 2024). "TRPC1 was implicated in glioma cell migration in response to growth factors EGF (epidermal growth factor) and PDGF (platelet-derived growth factor)." (PMID 36768856, 2023). "In particular, the epidermal growth factor (EGF) is secreted by glioma-associated microglia and macrophages (GAMs), which infiltrate the GBM-violated brain tissue continuum and participate in paracrine loops within glioblastoma niches." (PMID 32443749, 2020). "IL-1β, IL-6, TGF-β, and EGF have been shown to promote glioma invasion from tumor-associated macrophage secretion." (PMID 31300060, 2019). "Like NHE1 or NCKK, TRPC1 channels were localized to lipid raft domains at the leading edge of migrating glioma cells, and shRNA-mediated TRPC1 knockdown resulted in loss of EGF-induced glioma cell migration." (PMID 25852478, 2015). "In summary, this meta-analysis suggested that the EGF +61G/A polymorphism is associated with glioma development risk." (PMID 24740103, 2014). "Some studies have reported the association between polymorphism in EGF +61G/A and glioma susceptibility, but the results of these studies are not consistent." (PMID 24740103, 2014). "Our approach allowed us to look for potential glioma grade differences in the association between EGF +61G/A polymorphism and glioma risk." (PMID 24740103, 2014). "As we expected, the analysing results showed the consistent and significant associations between the EGF +61G/A polymorphism and glioma susceptibility in in all genetic models." (PMID 24740103, 2014). "Overall, this meta-analysis showed significant associations between the EGF +61G/A polymorphism and glioma susceptibility in all four genetic models." (PMID 24740103, 2014). "As the literature reported, EGF +61G/A polymorphism is also probably associated with the survival time of glioma patients." (PMID 24740103, 2014). "The results of this meta-analysis suggested that the EGF +61G/A polymorphism is associated with both the susceptibility of glioma and the malignance of glioma." (PMID 24740103, 2014). "Extensive studies have found that a single nucleotide polymorphism (SNP) +61G/A (rs4444903) in the EGF gene is associated with the susceptibility of glioma, however, the results have been controversial." (PMID 24740103, 2014). "We think this result will strengthen the previous knowledge about EGF +61G/A polymorphism and glioma risk." (PMID 24740103, 2014). "So a strict analysis of the association of EGF +61G/A polymorphism and glioma risk should be performed." (PMID 24740103, 2014). "Nine studies testing the associations between EGF +61G/A polymorphism and risk of glioma with 1758 cases and 2823 controls were retrieved." (PMID 24740103, 2014). "Many retrospective studies have shown that polymorphism in EGF or EGFR genes strongly correlates with susceptibility to glioma." (PMID 24740103, 2014). "Overall, significant associations between the EGF +61G/A polymorphism and glioma risk were observed in all genetic models (a versus A, OR = 1.22, 95% CI = 1.11–1.33; aa/Aa versus AA, OR = 1.21, 95% CI = 1.06–1.38)." (PMID 24740103, 2014). "Because of the limited analysing data, we can only conclude that EGF +61G/A polymorphism is related to high grade gliomas." (PMID 24740103, 2014). "To date, a number of studies have reported the association between the EGF +61G/A polymorphism and glioma risk, but the results were inconclusive." (PMID 22829952, 2012). "In contrast, the EGF +61G/A polymorphism was associated with a significant decreased risk of glioma in homozygote comparison (AA versus GG, OR = 0.66, 95% CI = 0.49–0.88) and dominant model (AA/GA versus GG, OR = 0.73, 95% CI = 0.58–0.93)." (PMID 22829952, 2012).
glioma (continued). "This meta-analysis examined all the available data on the association between the EGF +61G/A polymorphism and glioma risk, including a total of 1,613 glioma cases and 2,267 controls." (PMID 22829952, 2012). "The aim of this study was to perform a meta-analysis of eligible studies to derive precise estimation of the association of EGF +61G/A with glioma risk." (PMID 22829952, 2012). "Our findings are in line with those of a recently published meta-analysis showing that the EGF 61*G/G genotype in Caucasians is associated with increased risk of glioma, and recurrence of liver metastases." (PMID 22403631, 2012). "In this study, we analyzed single nucleotide polymorphism of EGF +61G/A in 677 patients with glioma and 698 gender- and age-matched controls." (PMID 20487573, 2010). "The result showed that the power was 0.964 in never-smokers, which was of strong ability to test the association between EGF +61 G/A and glioma." (PMID 20487573, 2010). "The association between EGF +61 SNP (rs4444903) and risk of gliomas is biologically plausible, since EGF performs a very important role in the proliferation, migration, and differentiation." (PMID 20487573, 2010). "The additive model (G/G vs G/A vs A/A) showed that both G/A and A/A genotype increased glioma risk (adjusted OR = 1.40, 95% CI: 1.17-1.66, p = 0.0002).G/A and A/A genotypes or EGF +61 A allele increased risk in both low and high WHO grade glioma." (PMID 20487573, 2010). "Our study indicated that G/A and A/A genotypes or EGF +61 A allele were associated with higher glioma risk in Chinese." (PMID 20487573, 2010). "Several genes are associated with CpG sites that drastically differ in methylation, shown in dark blue (unmethylated) and dark red (methylated), among them, ERBB2, a member of the epidermal growth factor (EGF) family and known to be associated with glioma susceptibility." (PMID 28768481, 2017). "There was a significant association between EGF +61A > G polymorphism and glioma risk among Asians." (PMID 26249370, 2015). "This study has an important implication for glioma progress prediction that genotyping for the EGF +61G/A variant might help in identifying patients at high risk of glioblastoma." (PMID 24740103, 2014). "Meta-analysis of the association between EGF +61G/A polymorphism and glioma risk." (PMID 24740103, 2014). "Additionally, we found that this association was more prominent in glioblastoma than in Grade I-III glioma, showing that the EGF +61G/A polymorphism is not only associated with the susceptibility to glioma, but also with the malignance of glioma." (PMID 24740103, 2014). "Since glioma grade is the most informative factor for stratification into subgroups with different prognoses, We speculated that EGF +61G/A polymorphism may be associated with the glioma grade." (PMID 24740103, 2014). "We examined the association of EGF +61G/A polymorphism and glioma by performing a meta-analysis." (PMID 24740103, 2014). "Therefore, a meta-analysis of nine case-control studies involving 1,758 cases and 2,823 controls was performed to drive a more precise estimation of the association of EGF +61G/A polymorphism with susceptibility to and severity of the glioma." (PMID 24740103, 2014). "Given the important roles of EGF in cell proliferation, differentiation or survival through binding to EGFR, it is biologically plausible that EGF polymorphism may modulate the risk of glioma." (PMID 22829952, 2012). "Our meta-analysis suggested that the EGF +61G/A polymorphism may be associated with an increased glioma risk among Asians, but a decreased glioma risk among Caucasians." (PMID 22829952, 2012). "Taken together, the results suggest that the EGF +61G/A polymorphism may contribute to the susceptibility of glioma in different ethnic groups." (PMID 22829952, 2012).